TSC1 (TSC complex subunit 1)
Diseases named in the same sentence as TSC1 in open-access papers (continued):
Sharing a sentence is not in itself a finding about the gene and the disease.
Duchenne muscular dystrophy (1 paper, 2023). Duchenne muscular dystrophy (DMD) is a neuromuscular disease characterized by rapidly progressive muscle weakness and wasting due to degeneration of skeletal, smooth and cardiac muscle. "PGT-M with NGS-based haplotype linkage analysis was performed for two families with maternal germline mosaicism for an X-linked Duchenne muscular dystrophy (DMD) mutation (del exon 45–50) or an autosomal TSC1 mutation (c.2074C > T)." (PMID 37270548, 2023).
ductal carcinomas (1 paper, 2017). "A polymorphic variant of TSC1 was associated with delayed age at diagnosis of ER-positive ductal carcinomas." (PMID 28122328, 2017).
E. coli Infection (1 paper, 2016). "In this study, we used a novel model of myeloid-specific Tsc1 deletion and constitutive mTORC1 activity to elucidate mTORC1 function in monocytes, which partly simulated monocytes behavior during E. coli infection." (PMID 27746591, 2016). "When mice were infected with E. coli, the expression of pS6K was also increased in monocytes of WT mice (WT + E. coli), indicating that E. coli infection activates mTORC1 pathway in monocytes and mTORC1-activated monocytes in bacterial infection can be simulated partly by TSC1 KO mice." (PMID 27746591, 2016). "In monocytes from TSC1 KO mice, the expression of CD40 is lower than in WT mice after E. coli infection, suggesting that the decreased expression of CD40 may lead, at least partially, to an ineffective activation of T cells." (PMID 27746591, 2016).
emphysema (1 paper, 2023). "Depletion of Tsc1 or Tsc2 in adult lung epithelium, smooth muscle, or vascular endothelium demonstrated that the activation of mTORC1 drove cell senescence, loss of lung alveolar structure, and the appearance of emphysema with pulmonary hypertension and significant vascular remodeling in male mice." (PMID 37874650, 2023).
endometrial tumors (1 paper, 2024). "PTEN mutations are found in 10% of central nervous system and endometrial tumors, TSC1 mutations in 5%–6% of urinary tract and endometrial tumors, and TSC2 mutations in 4%–7% of gynecological, liver, and lung tumors." (PMID 38515456, 2024).
fallopian tube carcinoma (1 paper, 2024). A carcinoma that arises from epithelial cells of the fallopian tube. "A report at the 2016 ASCO meeting showed a cohort of 379 patients with ovarian or fallopian tube carcinoma have been evaluated for 10 genes AKT1, AKT2, AKT3, mTOR, PIK3CA, PIK3C2B, PIK3R1, PTEN, TSC1, TSC2 in the PI3K/AKT/mTOR pathway." (PMID 38167649, 2024).
female infertility (1 paper, 2013). Diminished or absent ability of a female to achieve conception. "Disruption of Tsc1 introduced by Amhr2-cre caused defects in ovarian folliculogenesis, compromised oocyte/embryo integrity, obstruction of oviduct and failure of implantation, resulting in female infertility." (PMID 23335988, 2013). "It is noteworthy that Amhr2-cre previously used is not only expressed in granulosa cells, but also in the oviduct and uterus, so it is not confirmed whether specific deletion of Tsc1 in granulosa cells results in female infertility or not." (PMID 23335988, 2013).
focal cortical dysplasia type II (1 paper, 2023). "As mutations in TSC1 and TSC2, which cause partial-onset seizures associated with TSC, were found in focal cortical dysplasia type II (FCD II) patients, a clinical trial has been performed to explore the efficacy and safety of everolimus in FCD patients." (PMID 38074125, 2023).
gastric tumor (1 paper, 2023). "Among autophagy genes in the Reactome database, PRMT1 was negatively correlated with genes such as ATG9A, DYNC1H1, EPAS1, PINK1, TSC1, TUBB6, and ULK1 in gastric tumor tissues (STAD-TCGA) and positively correlated with HMMR, ESCO2, CHAC2, and NUDT6 (STAD-TCGA)." (PMID 37564212, 2023).
geographic atrophy (1 paper, 2021). "Similar to deletion of Tsc1, mice with deletion of Tsc2 in rods develop AMD-like pathologies, including accumulation of apolipoproteins, migration of microglia, geographic atrophy, and neovascular pathologies." (PMID 34208233, 2021).
glucosuria (1 paper, 2020). "We found that tight regulation of mTORC1 activity seems to be essential for physiological tubular transport functions: both mTORC1 activation (Tsc1 deletion) and inhibition (Raptor deletion) induced glucosuria and increased urinary KIM-1 and albumin excretion." (PMID 32726619, 2020).
hair follicle tumors (1 paper, 2012). "Since BCC are considered as hair follicle tumors, we additionally analyzed the cylindromatosis (CYLD) and tuberous sclerosis-1 (TSC1) genes, which both are TSGs known to be involved in classic hair follicle tumor syndromes." (PMID 23284750, 2012).
HCMV infection (1 paper, 2012). "Previous reports indicate that HCMV infection induces the levels of the Glut4 glucose transporter and the tuberous sclerosis protein (TSC1), a negative regulator of mTOR signaling." (PMID 22291597, 2012). "As previously reported, in the absence of inhibitor treatment, HCMV infection has little impact on TSC1 levels at 24 h post-infection but significantly increased the levels of TSC1 at 48 h post-infection and 72 h post-infection." (PMID 22291597, 2012).
heart failure (1 paper, 2020). Inability of the heart to pump blood at an adequate rate to meet tissue metabolic requirements. "Cardiac-specific overexpression of TORC1 increases stress-induced heart failure, whereas overexpression of Tsc1 and Tsc2 prevents the age-related increase of stress-induced heart failure." (PMID 31884871, 2020).
hereditary cancer (1 paper, 2025). Malignant neoplasms occurring in families at a rate greater than that expected by chance and caused by germline mutations in a specific gene. "LP/P findings in pleiotropic genes linked to human development and hereditary cancer (TSC1, PHOX2B, WT1, SPRED1, NF1, LZTR1, HOXB13) were identified in several patients with syndromic phenotypes." (PMID 40060932, 2025).
infantile epilepsy (1 paper, 2023). "Only a candidate variant (c.2742+5G>A, rs397515076) was found in a heterozygous state in the TSC2 gene, and no candidate variant was detected in the TSC1 gene or other infantile epilepsy-related genes." (PMID 37152430, 2023).
invasive candidiasis (1 paper, 2019). "Most interestingly, there was a significant difference in mortality between CD4+ T-cell-specific mTOR knockout and TSC1 knockout mice and wild-type mice with severe invasive candidiasis." (PMID 31668132, 2019). "For mice with severe invasive candidiasis, expression of LC3B and p62/SQSTM1 was higher in CD4+ T-cell-specific mTOR knockout mice but lower in CD4+ T-cell-specific TSC1 knockout mice compared with wild-type mice." (PMID 31668132, 2019).
iris hypoplasia (1 paper, 2017). "Taken together, these results demonstrate that conditional deletion of Tsc1 within the CM during eye development leads to CB and iris hypoplasia in postnatal mice." (PMID 28250050, 2017).
leukodystrophy (1 paper, 2016). Leukodystrophies are a group of rare, progressive, metabolic, genetic diseases that affect the brain, spinal cord and often the peripheral nerves. "This is plausible because we have previously shown in a rat model of inherited leukodystrophy that OLPs respond to TSC1 by moving forward from a progenitor stage to a pre-myelinating OL." (PMID 35558521, 2016). "Based upon BrdU incorporation we have previously shown that TSC1 mobilizes and triggers the proliferation of nestin-expressing progenitors in a rat model of leukodystrophy." (PMID 35558521, 2016).
lipoma (1 paper, 2026). A benign, usually painless, well-circumscribed lipomatous tumor composed of adipose tissue. "We observed a loss of heterozygosity in the lipoma tissue, resulting in TSC1 deficiency and subsequent activation of the mechanistic target of rapamycin (mTOR) signaling pathway." (PMID 42286631, 2026). "Further in vitro experiments showed that silencing TSC1 in adipocyte progenitors led to increased cell proliferation, supporting the hypothesis that TSC1 deficiency contributes to lipoma formation." (PMID 42286631, 2026).
liver failure (1 paper, 2019). A liver disease characterized by the liver losing or has lost all of its function. "Correspondingly, double knockout of the Tsc1 and Depdc5 genes provokes prominent upregulation of mTORC1, disrupts hepatocellular homeostasis, and subsequently precipitates oxidative injury and subsequent liver failure." (PMID 31754457, 2019).
liver fibrosis (1 paper, 2016). "Conversely, rapamycin can alleviated CCl4− induced liver fibrosis by inhibiting myofibroblast proliferation and inducing apoptosis, and rescued the specific phenomenon by TSC1 deficiency in the mesenchymal compartment." (PMID 27819329, 2016). "Thus, TSC1 deficiency in the mesenchymal compartment resulted in a significant increase in the abundance of myofibroblasts, thereby contributing to the noted exacerbation of liver fibrosis." (PMID 27819329, 2016). "The aim of this study is to examine the effects of conditional deletion of TSC1 in mesenchymal on pathogenesis of liver fibrosis." (PMID 27819329, 2016). "Increasing myofibroblast accumulation in TSC1 CKO mice in response to CCl4 treatment is thought to contribute to the noted significant increase in liver fibrosis." (PMID 27819329, 2016). "TSC1 CKO mice developed pronounced liver fibrosis relative to WT mice, as examined by ALT, hydroxyproline, histopathology, and profibrogenic gene." (PMID 27819329, 2016). "Collectively, these results demonstrated that TSC1 deletion in the mesenchymal compartment augments CCl4− induced liver fibrosis in mice." (PMID 27819329, 2016). "Consistent with enhanced liver fibrosis and collagen production, α-SMA positive staining was increased in CCl4− treated TSC1 CKO mice." (PMID 27819329, 2016).
lymphoproliferative disorder (1 paper, 2017). "In this paper, we demonstrated for the first time that Tsc1-deficient DCs resulted in the development of lymphoproliferative disorder, disturbed serum immune globulin and limited weight gain in mice, which indicates the role of Tsc1 in DCs in preserving immune tolerance." (PMID 28079897, 2017). "Here we show that selective disruption of Tsc1 in DCs results in a lymphoproliferative disorder with the spontaneous activation of T cells." (PMID 28079897, 2017).
malnutrition (1 paper, 2022). Inadequate nutrition resulting from poor diet, malabsorption, or abnormal nutrient distribution. "The deregulation in the activity of the TSC1 and LAMTOR2 gene was significantly associated with all forms of childhood malnutrition." (PMID 35458174, 2022).
medulloblastoma (1 paper, 2024). A malignant, invasive embryonal neoplasm arising from the cerebellum. "MYC amplification, which is a prevalent driver of group 3 medulloblastomas, and LOH deletion of a tumor suppressor, TSC1, was found in the PD2105 and PD2110 patients, respectively." (PMID 39322849, 2024).
muscle atrophy (1 paper, 2019). The loss of muscle tissue due to inactivity or disease. "Chronic activation of the mTORC1 pathway by muscle-specific deletion of Tsc1, a negative regulator of mTORC1, has been shown to cause late-onset myopathy with muscle atrophy in young adult mice." (PMID 31308131, 2019).
mycobacterial infection (1 paper, 2024). "Knockdown of miR-126 increases susceptibility to mycobacterial infection which can be independently reversed by targeting Tsc1/mTOR or ccr2 implicating macrophage function." (PMID 38307625, 2024). "The opposing effects of miR-126 knockdown and tsc1a knockdown on M. marinum burden suggested involvement of a potential miR-126/Tsc1 signalling axis in mycobacterial infection." (PMID 38307625, 2024). "We link infection-induced miR-126 to Tsc1 via activation of the mTOR pathway and improved macrophage function because of regulation of a Cxcl12/Ccl2/Ccr2 signalling axis during the early stages of mycobacterial infection." (PMID 38307625, 2024).
neuropathy (1 paper, 2021). A disorder affecting the nervous system that manifests with pain, tingling, numbness, and/or muscle weakness. "TSC2 mutations seemed more likely to have neuropathy than TSC1 in prenatal fetuses." (PMID 34513752, 2021).
ovarian failure (1 paper, 2015). "For larger follicles, mutant mice with disrupted TSC1 in granulosa cells of secondary follicles also exhibit enhanced follicle growth, leading to increased ovulatory capacity and delivery of more pups, followed by a premature ovarian failure phenotype." (PMID 25710488, 2015). "Studies using mutant mice indicated that oocyte-specific deletion of TSC1 or TSC2 promotes the growth of all primordial follicles in neonatal animals, leading to the exhaustion of the entire follicle pool, followed by a premature ovarian failure phenotype." (PMID 25710488, 2015).
pancreatic adenocarcinoma (1 paper, 2015). "Efficiency of TSC1 knockdown was examined in-vitro in NIH3T3 and TB11381PDA cells (a mouse pancreatic adenocarcinoma cell line); lentiviral infection with shTsc1-1 displayed the most efficient knockdown (~80%) and was selected for subsequent in-vivo experiments." (PMID 26046460, 2015).
Pancytopenia (1 paper, 2022). An abnormal reduction in numbers of all blood cell types (red blood cells, white blood cells, and platelets). "Ablation of both SZT2 and TSC1 results in rapid HSC exhaustion, pancytopenia, and premature death of mice in a mTORC1-dependent manner." (PMID 36250465, 2022). "Furthermore, ablation of both SZT2 and TSC1 — 2 repressors of mTORC1 on the nutrient and growth factor arms, respectively — led to rapid HSC depletion, pancytopenia, and premature death of the mice." (PMID 36250465, 2022).
pneumothorax (1 paper, 2025). Abnormal presence of air in the pleural cavity. "In LAM, abnormal proliferation of smooth muscle-like cells and destruction of the lung parenchyma caused by TSC1 or TSC2 gene mutations increase the fragility of lung tissue and the risk of pneumothorax." (PMID 39934870, 2025).
PTEN hamartoma tumor syndrome (1 paper, 2024). An autosomal dominant syndrome caused by pathogenic variants in the PTEN gene, characterized by hamartomas, overgrowth, neurodevelopmental disorders and an increased risk of various cancers, including breast, thyroid, and endometrial cancer. "PTEN is very similar to TSC1/2 in that it is also an upstream negative regulator of mTOR, and heterozygous variants lead to PTEN Hamartoma Tumor Syndrome (PHTS)." (PMID 39881808, 2024).
rosacea (1 paper, 2021). A chronic erythematous skin disorder that affects the face. "Here, we showed that TSC2 rather than TSC1 was significantly decreased in the lesional skin of rosacea, suggesting that declined TSC2 might be responsible for the hyperactivation of mTORC1 in rosacea." (PMID 33734592, 2021).
sarcoidosis (1 paper, 2020). Sarcoidosis is a multisystemic disorder of unknown cause characterized by the formation of immune granulomas in involved organs. "A decreased expression of TSC1 was observed in 33% of the sarcoidosis patients studied, leading to increased mTORC1 activation." (PMID 32760396, 2020).
sinonasal carcinoma (1 paper, 2022). "A locus-specific loss of heterozygosity in the PEComa but not in the sinonasal carcinoma was identified, suggesting the causative role of the splice mutation in the PEComa pathogenesis, because we excluded known pathogenetic pathways characteristic to PEComas (TSC1/2, TFE3, RAD51B)." (PMID 35419288, 2022).
squamous cell carcinoma (1 paper, 2022). A carcinoma arising from squamous epithelial cells. "Although the severity of UF was not assessed in this study, a previous report showed severe squamous cell carcinoma-like UF in patients with a TSC1 frameshift mutation." (PMID 36232477, 2022).
status epilepticus (1 paper, 2023). Status epilepticus is defined as a continuous seizure lasting more than 30 min, or two or more seizures without full recovery of consciousness between any of them. "Mutations in the TSC1 and TSC2 genes have been reported as the genetic basis for the tuberous sclerosis disease complex, and TSC2 gene variation has been associated with status epilepticus in Chinese children." (PMID 37493735, 2023).
Still’s disease (1 paper, 2022). "Transcriptomic data from patients with Still’s disease suggest decreased expression of the mTORC1 inhibitors TSC1/TSC2 and an mTORC1 gene signature that strongly correlates with disease activity and treatment response." (PMID 36443301, 2022).
tauopathies (1 paper, 2024). "In case of TSC1, this has already been done, as rapamycin (a drug inhibiting mTOR, which is in turn activated by TSC1/2) was used in numerous studies for AD/tauopathies, but with ambiguous results." (PMID 38554150, 2024).
Thyroid carcinoma (1 paper, 2021). "Thyroid carcinoma (n = 6) was exclusively reported in six female patients, of which half had TSC1 mutations." (PMID 34229737, 2021).
tongue cancer (1 paper, 2006). A malignant neoplasm affecting the tongue. "In so doing, nine cases from among the 28 tongue cancers were identified that manifest TSC1 or TSC2 herteoduplexes upon DHPLC analysis." (PMID 16412252, 2006).
triple-negative breast carcinoma (1 paper, 2024). An invasive breast carcinoma which is negative for expression of estrogen receptor (ER), progesterone receptor (PR), and human epidermal growth factor receptor 2 (HER2). "ICB targeting LAG3 and PD-L1 simultaneously inhibits metastatic progression in preclinical triple negative breast cancer (TNBC) mouse models of NF1-, TSC1- or TGF-β RII- deficient tumors." (PMID 38997291, 2024). "ICB targeting LAG3 and PD-L1 in triple-negative breast cancer (TNBC) mouse models with NF1, TSC1, or TβRII deficient tumors showed significant efficacy." (PMID 38997291, 2024).
tuberculosis (1 paper, 2016). A chronic, recurrent infection caused by the bacterium Mycobacterium tuberculosis. "We further demonstrated that TSC1 conditional knockout mice infected with Mycobacterium tuberculosis, the causative agent of tuberculosis, resulted in less bacterial burden and a comparable level of inflammation when compared to wild type mice." (PMID 27387347, 2016).
urothelial carcinoma of the bladder (1 paper, 2021). "Cancers with higher rates of TSC1/TSC2 mutation include: urothelial carcinoma of the bladder and upper tract, with 6–10% incidence of TSC1 mutations and perivascular epithelioid cell tumors (PEComa) with up to 50% frequency of TSC2 and TSC1 mutations." (PMID 33891611, 2021).
uveal melanoma (1 paper, 2024). A melanoma derived from melanocytes of the uveal tract. "In contrast, BRAF-mutant uveal melanomas likely harbor a deformed TSC1/2 complex resulting from inactivating TSC2 phosphorylation at Ser664 by hyperactive MEK and ERK60." (PMID 39349825, 2024).
Ventricular arrhythmia (1 paper, 2025). "Specifically, miR-95 targets CALM1 and miR-130b targets TSC1, both of which are associated with ventricular arrhythmias." (PMID 41295584, 2025).
viral hepatitis (1 paper, 2021). An acute or chronic inflammation of the liver parenchyma caused by viruses. "Overall, this study supports a beneficial role of metformin for viral hepatitis and also provides mechanistic evidence for the involvement of TSC1/mTOR in the regulation of T cell functions, providing a solid evidence for the therapeutic potential of metformin in viral infection." (PMID 33968030, 2021). "Together, this study has revealed for the first time a hepatoprotective role of metformin in acute viral hepatitis via mechanisms that include restraining excessive T cell infiltration and activation in the liver, inhibiting the mTOR signaling via a TSC1-dependent manner in T cells." (PMID 33968030, 2021).
visual disorders (1 paper, 2017). "Furthermore, the Tsc1-ablated mouse model also provides a valuable resource for future studies concerning the molecular mechanisms underlying ASD and acts as a platform for evaluating therapeutic approaches for the treatment of visual disorders." (PMID 28250050, 2017).